BLOC1S5-TXNDC5 (BLOC1S5-TXNDC5 readthrough (NMD candidate))
Synonyms: MUTED-TXNDC5
Gene: Protein-coding gene on chromosome 6 (7,881,522 to 8,064,364, reverse strand). Ensembl gene ENSG00000259040.
Genetic constraint (gnomAD): Missense variants: 158 observed, 142.29 expected, observed/expected ratio (o/e) 1.11, 90% interval 0.98 to 1.27. Synonymous variants: 59 observed, 51.56 expected, observed/expected ratio (o/e) 1.14, 90% interval 0.93 to 1.42.